PROK2 (prokineticin 2)
Diseases named in the same sentence as PROK2 in open-access papers (continued):
Sharing a sentence is not in itself a finding about the gene and the disease.
cancer (21 papers, 2013 to 2025). A tumor composed of atypical neoplastic, often pleomorphic cells that invade other tissues. "We showed that the genes encoding ANPEP, PROK2, CHP2, PTPRM, AREG, and COL7A1 were differentially expressed between SRC and PC carcinomas." (PMID 35626106, 2022). "Genes encoding ANPEP, PROK2, CHP2, PTPRM, AREG, and COL7A1 showed significant differential expression in SRC and PC carcinomas." (PMID 35626106, 2022). "G−CSF also induces the release of Prok2 by neutrophils, which in turn promotes angiogenesis and cancer cell proliferation." (PMID 34070438, 2021). "Infiltrated neutrophils provided cancer cells with Bv8/Prok2 with a potent mitogenic activity to promote cancer cell growth in lungs." (PMID 32422991, 2020). "According to the IPA analysis in our study, PROK2 gene was a part of the top enriched network connected to hematological system development and function, cancer and cellular movement." (PMID 26313571, 2015). "In nude mice xenografted with human cancer cell lines (A-673, Calu-6, HM7, HPAC, Jurkat), Bv8/prokineticin-2 is upregulated in bone marrow neutrophils." (PMID 34301813, 2021). "Whereas there are nine rhythm genes (MTNR1B, NR1D1, RORB, RORA, OPN4, C1orf51, PROK2, SERPINE, and EGR3) that are differently expressed in the high and low MSI group in more than 1/3 cancer types." (PMID 31927791, 2020). "PROK2 along with PROK1 are chemokine-like proteins (attracting leukocytes to an inflammatory site) usually expressed by components of the innate immune system, such as macrophages with specific roles in host defence and angiogenesis during virus-related cancers." (PMID 33121134, 2020). "However, no reports have been published on the involvement of PROK2 in gastroenterological malignant tumors or its relationship with gastroenterological malignant tumors." (PMID 26317645, 2015).
infection (3 papers, 2016 to 2023). The state of being infected such as from the introduction of a foreign agent such as serum, vaccine, antigenic substance or organism. "To do this, we overexpressed Prok2 in primary-culture chondrocytes using Ad-Prok2 infection and evaluated the expression levels of key matrix-degrading enzymes, including MMP3, MMP13, and ADAMTS5, which play pivotal roles in cartilage degradation during OA pathogenesis." (PMID 38057865, 2023).
bacterial infections (2 papers, 2022 to 2024). "For the BALF neutrophils, we observed increased Fth1 and decreased Prok2 expression in the ARDS patients compared to at-risk patients who did not develop the syndrome, including patients with bacterial infections." (PMID 36513690, 2022).
cardiovascular disease (2 papers, 2016 to 2025). "The new finding in this study that prokineticin-2 is strongly associated with cardiometabolic risk factors including lipid disorders might help to offer better understanding of cardiometabolic disorders and cardiovascular diseases, and further improve the therapy in the future possibly." (PMID 26728949, 2016).
neurological disorders (1 paper, 2023). "In conclusion, these data are the first to describe that PROK1 and PROK2 can modulate the permeability of the blood–brain barrier, thus potentially contributing to the regulation of cerebrovascular function and its potential relevance in various neurological disorders." (PMID 37895111, 2023).
PROK2 also shares sentences with these, for which no sentence is quoted: Anosmia (4 papers); Arthritis (2); neurodegenerative disease (2); adenocarcinoma (1); anemia (1); appendicitis (1); autoimmune disease (1); bipolar disorder (1); cognitive decline (1); colon adenocarcinoma (1); colon tumour (1); colonic polyps (1); colorectal tumors (1); developmental delay (1); experimental autoimmune encephalomyelitis (1); genetic disease (1); glioblastoma (1); graft versus host disease (1); Hyperglycemia (1); hypopharyngeal cancer (1); irritable bowel syndrome (1); Knee Osteoarthritis (1); leishmaniasis (1); lung carcinoma (1); malaria (1); mood disorder (1); multiple sclerosis (1); Noonan syndrome (1); osteoarthritis (1); ovarian carcinoma (1).
A further 9 diseases each share a sentence with PROK2 in 1 paper.